NTSR1 (neurotensin receptor 1)
Diseases named in the same sentence as NTSR1 in open-access papers (continued):
Sharing a sentence is not in itself a finding about the gene and the disease.
breast carcinoma (13 papers, 2009 to 2025). "NT and NTSR1 have been implicated in breast cancer progression and high levels of pro NT in the blood is linked to a higher risk of breast cancer." (PMID 32336282, 2020). "In particular, NTSR1 expression is strongly associated with a worse survival and a higher incidence of distant metastases in lung and breast cancers." (PMID 26298774, 2015). "Palmitoylation serves as a novel pharmacological target for inhibiting mitotic signaling of NTSR-1 in breast cancer cells." (PMID 40977744, 2025). "In breast cancer, NTSR1-induced activation of EGFR and HER2 receptors rendered these cancers aggressive, yet highly responsive to lapatinib and metformin in mice." (PMID 28316623, 2017). "Accumulating evidences also confirm that the activation of NTS/NTSR1 complex results in cancer progression and poor prognosis in breast cancer, malignant pleural mesothelioma, and head and neck squamous cell carcinomas." (PMID 25644759, 2015). "In breast cancer cells, NTSR1 up regulation was the result of beta catenin cellular and nuclear delocalization." (PMID 25249545, 2014). "Neurotensin (NTS) and its high affinity receptor (NTSR1) are up regulated in 20% of breast cancers, and NTSR1 overexpression was shown to predict a poor prognosis for 5 year overall survival in invasive breast carcinomas." (PMID 25249538, 2014). "In breast cancer cells, NTSR1 activation alters many cellular effects having oncogenic characteristics including proliferation, survival, adherence, migration and invasion, with a synergic effect between NTS and EGF on cellular migration and invasiveness." (PMID 25249538, 2014). "Amongst the factors contributing to tumor aggressiveness, neurotensin (NTS) and its cognate high-affinity receptor (NTSR1) have been shown to contribute to breast cancer progression." (PMID 25249538, 2014). "In order to further evaluate the status of NTS and NTSR1 in breast cancer we studied their respective expression in 106 IDCs." (PMID 19156213, 2009). "in the “Ma” database studying 54 patients with breast carcinomas, NTSR1 is correlated with the recurrence at 5 years (p = 0.04)." (PMID 19156213, 2009). "Identification of breast cancer patients characterized by paracrine NTS/NTSR1 signaling pathway, as evidenced in the present study, will provide alternative strategies to improve the treatment of IDCs." (PMID 19156213, 2009). "In conclusion, based on a series of 106 patients with invasive ductal breast cancer, we provide evidence for NTS/NTSR1 as a contributor to breast cancer progression." (PMID 19156213, 2009). "A correlation between up regulated expression of NTSR1 with the higher grades was found studying 55 and 125 breast carcinomas, from the Ginestier and Sotiriou databases (p = 0.028 and 0.04), respectively." (PMID 19156213, 2009). "In the Chin gene profile, containing 118 frozen primary breast carcinomas, NTSR1 was found over expressed in stage IV carcinomas as compared to stage I with p = 0.003." (PMID 19156213, 2009). "These suggest that NTSR1 is a promising target for breast cancer treatment." (PMID 31874629, 2019). "In addition to cell growth, activation of NTSR1 induces cell migration, invasion, and metastasis in head and neck squamous cell carcinomas, glioblastomas and breast cancer cells." (PMID 26298774, 2015). "NTS and NTSR1 are concomitantly overexpressed in patients with breast cancer." (PMID 25249538, 2014). "We conclude that NTSR1 regulation may occur in breast cancer and participates in the neoplastic progression in up to 35% of all patients." (PMID 19156213, 2009). "Previous studies have shown that NTSR1 is highly expressed in tumor tissues compared with normal tissues and that its expression correlates with a poor prognosis in various kinds of tumors, including glioma, small cell lung carcinoma, endometrial carcinoma, and breast cancer." (PMID 33034134, 2021).
breast carcinoma (continued). "For example, a recent report showed that neurotensin (NTS) and its high affinity receptor (NTSR1) enhances EGFR, HER2, and HER3 activation, but lapatinib could reduce the tumour growth of breast cancer cells overexpressing NTS and NTSR1." (PMID 25691057, 2015). "Co expression of NTS, NTSR1, HER2 and HER3 was analyzed in breast cancer tissue microarrays (TMA)." (PMID 25249538, 2014).
colorectal cancer (10 papers, 2015 to 2025). A primary or metastatic malignant neoplasm that affects the colon or rectum. "Low expression of NTSR1 was associated with non-invasive growth of colorectal cancer." (PMID 32296631, 2020). "It has been reported that NTSR3 forms a complex with NTSR1 and modulates NTSR1-mediated signaling in the human colorectal cancer cell line HT29 (ref.35)." (PMID 40451927, 2025). "NTSR1 antagonists have been trialled in animal studies which demonstrated significant reduction in colorectal cancer growth in mice." (PMID 32764278, 2020). "An abundance of data implicate NTS and NTSR1 in the progression of several cancers, including pancreatic, breast, lung and colorectal cancers, and NTS is expressed at higher levels in cultured and primary CRC cells than in normal colon." (PMID 26334593, 2015). "This study demonstrated that NTS, NTSR1, and NTSR3 are detected in most colorectal cancer tissue." (PMID 32764278, 2020). "The current study demonstrated over-expression of NTS, NTSR1, and NTSR3 in colorectal cancers compared to surrounding normal epithelium." (PMID 32764278, 2020). "In vitro study published in 2015, focusing on human colorectal cancer cell lines corresponding to different colorectal cancer stages, showed variable NTS and NTSR1 expressions, no expression of NTSR2 and constant NTSR3 expression." (PMID 33268796, 2020).
glioma (10 papers, 2015 to 2024). A benign or malignant brain and spinal cord tumor that arises from glial cells (astrocytes, oligodendrocytes, ependymal cells). "Since NTS and NTSR1 expression was associated with the pathological grade of glioma, we investigated the possibility of NTS or NTSR1 as a prognostic marker for glioma patients." (PMID 25644759, 2015). "Among the gliomas, glioblastoma mutliforme (GBM) has the highest expression of NT and NTSR1 which in turn is associated with increased postoperative mortality." (PMID 32336282, 2020). "Our previous study demonstrated that NTS and NTSR1 are overexpressed in human glioma, and that the activation of NTS/NTSR1 signaling is associated with the progression of glioma." (PMID 30814514, 2019). "Among the gliomas, the highest expression of NT and NTSR1 occurs in GBM, which positively correlates with increased postoperative mortality." (PMID 29467963, 2018). "Prospective studies have been carried on in other cancers, for example, glioma, which demonstrated that increased NTS and NTSR1 expression is associated with significantly decreased 3-year survival." (PMID 28316623, 2017). "SR48692, a NTSR1 specific antagonist, inhibited the invasiveness of orthotopically implanted glioma cells in the mouse brain and prolonged the survival time of the experimental animals." (PMID 25644759, 2015). "We firstly reported that high levels of NTS or NTSR1 expression were correlated with a poor prognosis in the glioma patient, which would be a potential target for glioma treatment and need to be further investigated." (PMID 25644759, 2015). "NTS precursor (ProNTS), NTS and NTSR1 expression levels in glioma were detected by immunobloting Elisa and immunohistochemistry assay." (PMID 25644759, 2015). "Positive correlations were shown between the expression levels of NTS and NTSR1 with the pathological grade of gliomas." (PMID 25644759, 2015). "The NTS/NTSR1 were detected by immunohistochemistry (IHC) and the results confirmed that NTS/NTSR1 expression were obviously elevated in human glioma compared with the peritumoral tissue and the relative normal brain tissue." (PMID 25644759, 2015). "To visualize the expression of NTSR1 in glioma cells, we performed immunofluorescence staining in the malignant glioma cell lines GL261 and U87." (PMID 25644759, 2015). "The orthotopic glioma implantations were established to analyze the role of NTS and NTSR1 in glioma progression in vivo." (PMID 25644759, 2015). "Here, we detected the expression levels of NTS and NTSR1 in glioma specimens and investigated the relationship between the expression levels and the patients’ prognosis." (PMID 25644759, 2015). "NTS and NTSR1 are highly expressed in glioma tissue, especially in glioblastomas, and their expression levels are positively correlated with the pathological grade of the gliomas." (PMID 25644759, 2015). "We established intracranial orthotopic transplantation gliomas in mice, and analyzed the impact of the NTSR1 specific inhibitor SR48692 on the biological behaviors of the glioma cells and the survival time of the glioma-bearing mice." (PMID 25644759, 2015). "We first reported that high levels of NTS and NTSR1 expression predict a decreased survival rate in glioma patients." (PMID 25644759, 2015). "The IHC quantification showed that the expression level of NTS and NTSR1 was significantly high as the glioma pathological grade was increased." (PMID 25644759, 2015). "Western blot analysis showed that the expression of NTSR1 in glioma cells was significantly reduced following siRNA treatment." (PMID 25644759, 2015). "To further examine the role of NTSR1 in glioma cell proliferation promoted by NTS, we transfected an NTSR1 specific small interfering RNA (siRNA) into the glioma cells." (PMID 25644759, 2015). "Meanwhile, we tested the expression level of NTS and NTSR1 in the 30 glioma samples by IHC and western blot analysis." (PMID 25644759, 2015).
glioma (continued). "We found that high NTS and NTSR1 mRNA expression indicated a poor outcome in the Gravedeel dataset, which includes a cohort of 273 glioma patients." (PMID 25644759, 2015). "Both NT and NTSR1 is correlated with increasing glioma tumour grade." (PMID 32336282, 2020). "Expression of NT and NTSR1 in gliomas increases with increasing tumor grade." (PMID 29467963, 2018). "However, as a neuropeptide in the CNS, the potential biological functions of NTS/NTSR1 and their downstream signaling pathway in glioma are unclear." (PMID 25644759, 2015). "First, NTS can promote the proliferation and invasiveness of glioma cells directly through NTSR1." (PMID 25644759, 2015). "High expression levels of NTS and NTSR1 predict a poor prognosis in glioma patients." (PMID 25644759, 2015). "The high expression levels of NTS and NTSR1 indicate a worse prognosis in glioma patients." (PMID 25644759, 2015). "Additionally, we confirmed that the wound healing effect of glioma cells transfected with the NTSR1-siRNA was significantly decreased compared to the glioma cells of the control group." (PMID 25644759, 2015). "NTS promotes the proliferation and invasion of glioma via the activation of NTSR1." (PMID 25644759, 2015). "NTS and NTSR1 were mainly located at cytoplasm and cellular membrane of glioma cells." (PMID 25644759, 2015). "Mechanistically, NTSR1 increases C-MYC expression, extracellular signal-regulated kinase 1/2 (ERK1/2) phosphorylation, as well as the proliferation and migration of glioma cells." (PMID 37370851, 2023). "In glioma, expression of the high-affinity NTS G-protein-coupled receptor 1 (NTSR1) correlates directly with tumor grade and indirectly with survival." (PMID 37370851, 2023). "To examine the role of NTS and NTSR1 in the progression of glioma in vivo, we transplanted GL261 glioma cells into the brains of C57/BL6 mice to establish a syngeneic and orthotopic graft model." (PMID 25644759, 2015). "In turn, treatment with the NTSR1 inhibitor, SR48692, decreases growth of a murine glioma model." (PMID 37370851, 2023). "NTS stimulated Erk1/2 phosphorylation in glioma cells, which could be reversed by SR48692 or NTSR1-siRNA." (PMID 25644759, 2015). "The proliferation and invasiveness of glioma cells could be enhanced by NTS stimulation and impaired by the inhibition of NTSR1." (PMID 25644759, 2015).
lung adenocarcinoma (9 papers, 2014 to 2026). A carcinoma that arises from the lung and is characterized by the presence of malignant glandular epithelial cells. "According to the Kaplan–Meier plotter database, higher NTSR1 expression was associated with shorter overall survival in patients with lung adenocarcinoma." (PMID 37726723, 2023). "NTSR1 mRNA expression appeared to be an important survival factor in smoking-associated lung adenocarcinoma." (PMID 32764278, 2020). "NTSR1 is reportedly expressed in 40% of lung tumors, and its expression is a negative prognostic marker in patients with surgically resected stage I lung adenocarcinoma." (PMID 35962453, 2022). "NTSR1 present in the cytoplasm, as in lung adenocarcinoma is correlated with a poor prognosis, however, if it is located on the cell surface, as in lung squamous cell carcinoma, then NTSR1 has no bearing on prognosis." (PMID 32336282, 2020). "In a previous clinical study, NTSR1 overexpression was applied to predict a poor prognosis for 5-year OS in a stage I lung adenocarcinomas population treated by surgery alone." (PMID 33414898, 2020). "Using flow cytometry and fluorescence microscopy, we were able to confirm the active involvement of NTSR1 in the uptake of these anti-NTSR1-mAb functionalized hybrid nanoparticles by lung adenocarcinoma cells." (PMID 26410728, 2015). "Using anti-mutant KRAS-siRNA, and siGLO-green as our model siRNAs, we hoped to verify the involvement of NTSR1 in the internalization of siRNA-loaded hybrid nanoparticles in A549 and H23 lung adenocarcinoma cell lines." (PMID 26410728, 2015). "Following the successful conjugation of anti-NTSR1-mAb to the surface of the hybrid nanoparticles, it was essential to confirm the involvement of NTSR1 in the uptake of these nanoparticles by lung adenocarcinoma cells known to overexpress this receptor." (PMID 26410728, 2015). "NTSR1 has been shown by immunohistochemistry to be overexpressed in approximately 60 % of lung adenocarcinoma." (PMID 26410728, 2015). "The involvement of the target receptor (NTSR1) in the uptake of these nanoparticles by lung adenocarcinoma cells was confirmed using both fluorescent microscopy and flow cytometry." (PMID 26410728, 2015). "In the lung adenocarcinomas, NTSR1 staining of cancer cells was granular, intracellular, heterogeneous and rarely localized at the plasma membrane." (PMID 25249545, 2014). "In a second study, shown here, the frequent and high expression of NTSR1 was correlated with a pejorative prognosis in 389 patients with stage I to III lung adenocarcinoma, and was an independent prognosis marker." (PMID 25249545, 2014). "In a previous clinical study, NTSR1 overexpression was shown to predict a poor prognosis for 5 year overall survival in a selected population of stage I lung adenocarcinomas treated by surgery alone." (PMID 25249545, 2014). "The same research group showed that high expression of NTSR1 was an independent negative prognostic marker in 389 patients with lung adenocarcinoma, stages I to III." (PMID 32336282, 2020). "NTSR1 high expression is a negative prognostic marker in a selected population of stage I lung adenocarcinomas, treated by surgery alone, and in ductal invasive carcinomas." (PMID 25249545, 2014). "A preliminary work of our team, suggested that the NTSR1 expression is a negative prognostic marker in a selected population of stage I lung adenocarcinoma treated by surgery alone." (PMID 25249545, 2014).
Anxiety (7 papers, 2018 to 2024). Intense feelings of nervousness, tension, or panic often arise in response to interpersonal stresses. "In a dental research study of 2022, the NTSR1 gene was found to relate to another form of fear, dental care-related fear and anxiety (DFA), which is linked to poor oral health and decreased quality of life." (PMID 37534788, 2024). "Since anxiety and depression are closely linked with disturbances in sleep, the neurotensinergic system may contribute to a common shared pathway involved in both sleep and affective disorders, which includes NTSR1." (PMID 37534788, 2024). "NT, NTSR1, and NTSR2, are present in several brain regions that are implicated in anxiety and depression, such as the prefrontal cortex, amygdala, and hippocampus." (PMID 37534788, 2024). "Stress responses and anxiety involve mainly NTSR1, but also NTSR2 and NTSR3." (PMID 37534788, 2024). "Furthermore, neurotensin receptor 1 (Ntsr1) knockout mice also showed increased anxiety and despair behaviors." (PMID 37275985, 2023). "We used open field chambers to determine whether developmental deletion of NtsR1 from DA neurons impacts DA-dependent locomotor activity and anxiety behaviors." (PMID 36213756, 2022). "NTSR1 (neurotensin receptor 1) knockout mice showed increased despair and anxiety." (PMID 36004833, 2022). "Furthermore, following sleep deprivation, NTSR1 knockout mice (C57BL/6N wild-type mice with a targeted Ntsr1 mutation) exhibited more wake and less NREM rebound sleep, and also showed increased anxiety and despair behaviors." (PMID 33192958, 2020). "Mice null for NtsR1 may therefore suffer from abnormal formation of the VTA DA system that causes aberrant DA signaling, locomotor activity, body weight, anxiety, sleep, and exaggerated response to psychostimulants that has been reported to occur in this line." (PMID 29464190, 2018). "However, since modulating VTA DA signaling has been implicated in weight loss by promoting anxiety, aversion or reinforcement, we also evaluated whether deleting VTA NtsR1 causes such adverse DA-associated physiology." (PMID 36213756, 2022). "In a relevant model, treatment for 6 h with the hypothermia-inducing NTSR1 agonist HPI-363 45 min following stroke prevented long-term depression and anxiety-like behaviors examined at 6 weeks post-stroke." (PMID 37534788, 2024). "Neither did developmental NtsR1 deletion alter operant responding for sucrose (a DA-dependent behavior), or anxiety as assessed by multiple measures." (PMID 36213756, 2022). "This is also consistent with activation of VTA NtsR1 neurons, which also did not invoke anxiety or aversion behaviors." (PMID 36213756, 2022). "We next used open field chambers to assess whether adult-onset deletion of NtsR1 from VTA DA neurons altered DA-dependent locomotor activity and anxiety behaviors." (PMID 36213756, 2022). "Since DATR1Null mice and NtsR1flox/flox controls spent comparable percentage of time in the periphery, it suggests that the developmental deletion of NtsR1 does not invoke anxiety-like movement." (PMID 36213756, 2022). "Even though the antagonist showed efficacy on only some, and not all, anxiety-related responses, the authors claimed that NTSR1 blockade can play a role in the adaptative responses to unavoidable or extreme stress events, and could be useful in affective disorder and anticipatory anxiety." (PMID 37534788, 2024).